GLI3 (GLI family zinc finger 3)
Diseases named in the same sentence as GLI3 in open-access papers (continued):
Sharing a sentence is not in itself a finding about the gene and the disease.
germ cell tumor (1 paper, 2020). A benign or malignant, gonadal or extragonadal neoplasm that originates from germ cells. "Although no experiments were performed that directly identify GLI3 as an oncogenic protein in germ cell tumors, the higher GLI3 copy numbers in germ cell tumors is indicative of more HH activation and SHH related gene expression which is known to drive tumor growth and progression." (PMID 32245491, 2020).
hearing loss (1 paper, 2021). "We observed that several SNPs in SCARNA16, IQGAP2, PTPRK, GLI3, ADARB2 and NDUFV2, which have been reported to be significantly associated with several other types of hearing loss, were also significantly associated with NIHL in this study (all P values ≤ 0.05)." (PMID 33242228, 2021).
Hepatic steatosis (1 paper, 2016). Steatosis is a term used to denote lipid accumulation within hepatocytes. "In case of down-regulated Gli1 and Gli3, prominent lipogenic transcription factors (e.g. Ppara/g, Srebf1) are up-regulated and influence an entire network of several genes associated with lipid metabolism which finally ends up with hepatic steatosis." (PMID 27185526, 2016).
hereditary hemochromatosis (1 paper, 2025). An inherited metabolic disorder characterized by iron accumulation in the tissues. "Some genes, like GLI3, have been linked to both post-axial polydactyly and hereditary hemochromatosis." (PMID 40568254, 2025).
hydrolethalus syndrome (1 paper, 2020). Hydrolethalus (HLS) is a severe fetal malformation syndrome characterized by craniofacial dysmorphic features, central nervous system, cardiac, respiratory tract and limb abnormalities. "These include Pallister‐Hall syndrome (PHS), as well as HPE9 and Culler‐Jones syndrome (CJS), due to dominant mutations in the GLI3 and GLI2 genes, respectively, and hydrolethalus syndrome related to recessive mutations in HYLS1 and KIF7." (PMID 31840946, 2020).
Hyperkeratosis (1 paper, 2019). Hyperkeratosis is a histopathological term defining a thickened stratum corneum and may be present in many different skin conditions, with many possible overlaps. "After Oxa treatment, Gli3+/– mice had attenuated epidermal and dermal thickening with decreased hyperkeratosis and parakeratosis compared with WT mice, and serum IgE levels were significantly decreased." (PMID 31264977, 2019).
Hypodontia (1 paper, 2013). The absence of five or less teeth from the normal series by a failure to develop. "In a previous study, we found the association between twors929387 of GLI3 and non-syndromic hypodontia." (PMID 24278334, 2013). "One of our studies suggests the potential relationship between polymorphism in rs929387 of GLI3 and non-syndromic hypodontia." (PMID 24278334, 2013). "Our results show that polymorphism in rs929387 of GLI3 associated with tooth agenesis in Chinese Han population, especially in male." (PMID 24278334, 2013). "The data demonstrate a strong relationship between the marker rs929387 of GLI3 and sporadic oligodontia tooth agenesis in the Han population and implicated allele C as its risk factor." (PMID 24278334, 2013). "In a previous study, we observed that polymorphism in rs929387 of GLI3 might be associated with hypodontia in the Chinese Han population based on a limited population." (PMID 24278334, 2013). "In a previous study, we observed that polymorphism in rs929387 of GLI3 might be associated with hypodontia in Han population." (PMID 24278334, 2013). "The results further confirm our previous conclusion that polymorphisms on rs929387 of GLI3 may be a risk factor for Chinese Han population with tooth agenesis." (PMID 24278334, 2013). "In summary, in this study, we demonstrate that polymorphism in rs929387 of GLI3 may contribute to the sporadic non-syndromic tooth agenesis in Chinese Han people." (PMID 24278334, 2013). "Furthermore, GLI3 can be regarded as a marker gene for the risk of tooth agenesis." (PMID 24278334, 2013). "However, more experiments may be need to elucidate the regulatory mechanism of GLI3-mediated tooth agenesis." (PMID 24278334, 2013).
Infertility (1 paper, 2018). "The biological processes significantly represented among differentially expressed genes included mitochondrial function (Mrps31 and Trit1), cell senescence (Gpx6, Lamtor1 and Hist1h1e), cell growth (Hormad1 and Hormad2), infertility (Sycp3), and embryo development (Gli3)." (PMID 29851234, 2018).
large cell carcinoma (1 paper, 2013). A malignant epithelial neoplasm composed of large, atypical cells. "In H520 squamous lung carcinoma cells and in large cell carcinoma cells (data not shown), the specific silencing of Gli1, Gli2 or Gli3 had a similar effect in cell proliferation and cyclin expression." (PMID 23667589, 2013).
leukemia (1 paper, 2020). A malignant (clonal) hematologic disorder, involving hematopoietic stem cells and characterized by the presence of primitive or atypical myeloid or lymphoid cells in the bone marrow and the blood. "Even though GLI3 silencing has never been described in the context of Ara-C resistance in AML, the association of HH pathway activity with chemotherapy resistance is well established in leukemia and other cancers." (PMID 32708452, 2020).
mesenchymal tumor (1 paper, 2016). "Given that the Hedgehog pathway has been shown to control the development of the mouse gut mesenchyme, we sought to determine whether two commonly studied murine models of the mesenchymal tumor GIST express key Hedgehog signaling components (Shh, Ihh, Ptch1, Smo, Gli1, Gli2, Gli3)." (PMID 27793025, 2016).
microphthalmia (1 paper, 2006). Congenital or developmental anomaly in which the eyeballs are abnormally small. "With regards the requirement for Gli3 in eye development,Gli3-/- embryos exhibit a variety of eye abnormalities ranging from microphthalmia to the absence of any remnant of eye tissue." (PMID 17029624, 2006).
Oligodontia (1 paper, 2013). The absence of six or more teeth from the normal series by a failure to develop. "To further confirm this observation, in this study, we employed 89 individuals diagnosed with sporadic non-syndromic oligodontia (40 males and 49 females) to investigate the relationship between polymorphism in rs929387 of GLI3 and tooth agenesis." (PMID 24278334, 2013).
Opitz BBB/G syndrome (1 paper, 2009). "Furthermore, they provide a molecular explanation for the phenotypic overlap between Opitz syndrome patients with dysregulated PP2A-activity and syndromes caused by GLI3-mutations." (PMID 19829694, 2009).
ovarian tumors (1 paper, 2016). "Consistent with previous results, GLI1 and GLI3 (HH pathway transcriptional effectors), PTCH1 (HH signaling repressor and target gene), SMO (HH signaling activator), IHH and SHH (HH pathway ligands) were expressed in ovarian tumors, albeit at variable levels." (PMID 26755648, 2016).
pancreatic adenocarcinoma (1 paper, 2023). "Downstream, the Hh pathway also activates Gli3, a known transcription inhibitor, and Gli3 mutation has been linked to pancreatic adenocarcinoma." (PMID 37305676, 2023).
pancreatic ductal adenocarcinoma (1 paper, 2023). An infiltrating adenocarcinoma that arises from the epithelial cells of the pancreas. "Subcutaneous injection of a murine pancreatic ductal adenocarcinoma cell line (KPC) with mouse Gli2/Gli3-knock-out (KO) fibroblasts in mice led to a reduction in tumor growth, decreased the recruitment of MDSCs and increased NK cells." (PMID 36674836, 2023). "In an invasive model of pancreatic ductal adenocarcinomas (PDA), the ablation of Gli2 and Gli3 in fibroblasts was shown to decrease tumor growth by recruiting NK cells during the late stages of tumorigenesis." (PMID 36674836, 2023).
Parkinson disease (1 paper, 2022). A progressive degenerative disorder of the central nervous system characterized by loss of dopamine producing neurons in the substantia nigra and the presence of Lewy bodies in the substantia nigra and locus coeruleus. "Other interesting associations reported in the GWAS catalogue include Parkinson’s disease (LZB3), educational attainment (FRZB and GLI3) and ADHD/Externalising behaviour (HERC1)." (PMID 36415660, 2022).
Primary amenorrhea (1 paper, 2022). "We also identified a GLI3 missense variant in patient Fc-M-8, who was diagnosed with type I MRKH syndrome (ESHRE classification: U5bC4V4) with primary amenorrhea and dyspareunia." (PMID 35361250, 2022).
Retinal dysplasia (1 paper, 2006). Abnormal growth and differentiation, structure and appearance of the retina present from birth. "The majority of Gli3+/- animals (22/25) showed no retinal dysplasia; a small proportion (3/25) did exhibit focal retinal hyperplasia." (PMID 17029624, 2006).
retinopathy of prematurity (1 paper, 2024). A bilateral retinopathy characterized by neovascularization, scarring, retinal detachment, and eventually blindness. "A GWAS in a multi-ethnic cohort identifies a novel association between the GLI3 SNP rs2058019 and retinopathy of prematurity (ROP) severity, which was confirmed as relevant to preretinal neovascular disease and human ocular gene expression." (PMID 38233474, 2024).
sarcoma (1 paper, 2022). A usually aggressive malignant neoplasm of the soft tissue or bone. "The specific expression of genes obtained from the annotation of highly correlated methylation site features, such as PRKAR1B, INPP5A, and GLI3, was proven to be associated with sarcoma by publications." (PMID 36619306, 2022). "Therefore, expression changes caused by the aberrant methylation of GLI3 may serve as a basis for the classification of sarcomas." (PMID 36619306, 2022). "Through such method, genes highly associated with sarcoma subtypes, such as PRKAR1B, INPP5A, GLI3, and other genes, were obtained." (PMID 36619306, 2022).
steatosis (1 paper, 2016). Increased lipid within the cytoplasm of cells. "However, the combination of GLI1 and GLI3 significantly mitigated the steatosis in the hepatocytes from ob/ob mice indicating that parallel changes in both GLI factors are required to reverse steatosis." (PMID 27185526, 2016). "Furthermore, the obvious down-regulation of Gli1 and Gli3 in human livers with steatosis supports the universality of the postulated 'steatotic Gli-code' and reveals new insights in the regulation of hepatic lipid metabolism." (PMID 27185526, 2016). "Using transgenic mice with conditional hepatocyte-specific deletion of Smoothened in adult mice, we showed that hepatocellular inhibition of Hedgehog signaling leads to steatosis by altering the abundance of the transcription factors GLI1 and GLI3." (PMID 27185526, 2016). "Ad (iii), to proof the assumption that reversal of the level of the Gli TFs (GLI1 and GLI3) is able to overcome steatosis we treated isolated hepatocytes from steatotic ob/ob mice with overexpression plasmids for GLI1, GLI2, GLI3 and a combination of GLI1 and GLI3." (PMID 27185526, 2016).
synpolydactyly (1 paper, 2022). A joint presentation of syndactyly (fusion of digits) and polydactyly (production of supernumerary digits). "In contrast to GLI3, similar observational studies of HOXD13 revealed that its disruption was linked to many different digital malformations, including synpolydactyly (SPD1; MIM: 186000), brachydactyly type D (BDD; MIM: 113200), and brachydactyly type E (BDE; MIM: 113300)." (PMID 36035248, 2022).
thyroid cancer (1 paper, 2023). "Data on GLI3-driven molecular mechanisms in thyroid cancer are not available." (PMID 37208504, 2023).
Tracheomalacia (1 paper, 2020). "Gli2−/−;Gli3+/− mouse embryos that have only one copy of Gli3 also exhibit tracheomalacia, whereas Gli2+/−;Gli3−/− embryos, which lack Gli3 but have a single copy of Gli2, do not." (PMID 33328171, 2020). "PHS patients, with a mutated copy of GLI3 that leads to excessive GLI3R, frequently present with tracheomalacia." (PMID 33328171, 2020). "Similarly, Gli2−/−;Gli3+/− germline mouse mutants, with one copy of Gli3R but no Gli2A, displayed tracheomalacia, whereas Gli2+/−;Gli3−/− mice, which lack Gli3R, do not." (PMID 33328171, 2020).
ulcerative colitis (1 paper, 2022). An inflammatory bowel disease involving the mucosal surface of the large intestine and rectum. "We chose two large cohorts of patients with ulcerative colitis and found significant upregulation of SMO and GLI3 in ulcerative colitis patients compared to healthy controls." (PMID 35835905, 2022).
ventricular septal defect (1 paper, 2025). The presence of a defect (opening) in the septum that separates the two ventricles of the heart. "NF1 and GLI3 are both linked with multiple forms of CHDs, including atrial and ventricular septal defects, which are common forms of CHDs that are also associated with CHD genes such as NKX2–5 and TBX5." (PMID 40857331, 2025).
tumor (59 papers, 2011 to 2025). "Loss of GLI repressor (via Gli3 deletion) reduces the migration of macrophages and decreases tumor growth, demonstrating that HH activation can antagonize PDA." (PMID 35867772, 2022). "In invasive tumors, we have determined that the loss of Gli2 and Gli3 in fibroblasts decreases myeloid-derived suppressor cells (MDSCs) and increases natural killer (NK) cells, which in turn antagonize tumor growth." (PMID 35867772, 2022). "Additionally, loss of Gli3 in fibroblasts reduces suppressor cells derived from myeloid lineages and enhances natural killer cell activity, thereby inhibiting tumor growth." (PMID 41018112, 2025). "Activation of stromal Hh pathway could occur as a result of local paracrine signals from the morphoeic tumour or be related to the mutated stroma itself including GLI3." (PMID 41373535, 2025). "NK cell depletion reversed the tumor-suppressive effect of Gli2/Gli3 loss, restoring tumor growth." (PMID 39859231, 2025). "Notably, the depletion of NK cells in tumors co-injected with Gli2/Gli3 KO fibroblasts rescues tumor growth, suggesting that the loss of Gli2/Gli3 in fibroblasts restrains tumor growth through the recruitment of NK cells." (PMID 36674836, 2023). "Importantly, multiple lines of evidence associate the overexpression of GLI3 with poor prognosis in various tumor types." (PMID 36981021, 2023). "PTCH1 and GLI3 overexpression could be caused by a self-inhibiting mechanism of the pathway, since they are a tumor suppressor and a repressor effector, respectively." (PMID 30754660, 2019). "Since all patients underwent chemotherapy (containing 5-FU), this correlation further support our hypothesis that high expression of GLI1/GLI3 molecules in the tumor indicates poor outcomes from 5-FU associated chemotherapy treatment." (PMID 28413604, 2017). "Since anchorage-independent growth is tightly associated with tumor development, we then determined whether Set7-mediated Gli3 methylation affects this feature." (PMID 27146893, 2016). "Gli2 and Gli3 are key mediators of Hedgehog signaling that regulate various cellular processes, including tumor–stroma interactions and immune modulation." (PMID 39859231, 2025). "This indicates that combined Gli2/Gli3 deletion in fibroblasts suppresses tumor growth specifically through enhanced NK cell recruitment." (PMID 39859231, 2025). "WES of one eyelid mBCC tumour–stroma pair identified 150 shared nonsynonymous mutations—representing 76.5% of all stromal mutations—including mutations in ATR, EPHA3 and GLI3." (PMID 41373535, 2025). "The results showed a substantial decrease in tumor growth in mice implanted with GLI3-knockout cells." (PMID 39998882, 2025). "We further showed that in GC cells, depletion of GLI3 attenuated cellular proliferation rate and invasiveness while using mouse models; the role of GLI3 driving tumor growth and metastasis in vivo was also clearly observed." (PMID 39998882, 2025). "Taken together, our results indicate that GLI3 possesses an oncogenic potential to promote GC cell proliferation and invasiveness in vitro and enhances tumor growth and metastasis in vivo." (PMID 39998882, 2025). "We show that staining of GLI1, KRT16, and S100A7 appears in the same places in the samples (same samples and different tumor slices) in all stages, while the localization of staining of GLI3 differs from the other proteins at lower stages." (PMID 38892279, 2024). "GLI1 and GLI3 were significantly positively correlated in 21 tumor tissues but negatively correlated in one tissue." (PMID 38498906, 2024). "GLI1 and GLI2 have been found to have overlapping effects on tumor development, while the relationship between GLI3 and the former two is not yet fully understood." (PMID 38498906, 2024). "Comparing the expression of the CDDP-DTP-associated genes between tumor and normal adjacent tissue, and its clinical relevance, we found that six (GADD45A, SOCS1, EPS15, GLI3, NR2F2, and RCOR1) of the hub genes have significant differences." (PMID 37916165, 2023).